DEFB104A (defensin beta 104A)
Description:
Has antimicrobial activity. Synergistic effects with lysozyme and DEFB103.
Synonyms: BD-4; DEFB-4; hBD-4; DEFB104; DEFB4
Tractability: Antibody: UniProt places it where antibodies can reach, with medium confidence; UniProt predicts a signal peptide or a membrane-spanning region; its Gene Ontology location is reachable by antibodies, with medium confidence.
Gene: Protein-coding gene on chromosome 8 (7,836,436 to 7,841,242, forward strand). Ensembl gene ENSG00000176782.
Subcellular location: Secreted
Pathways (Reactome):
Immune System: Beta defensins; Defensins
Gene Ontology:
Molecular function: chemoattractant activity
Biological process: cellular response to phorbol 13-acetate 12-myristate; defense response to Gram-negative bacterium; defense response to Gram-positive bacterium; innate immune response; monocyte chemotaxis; positive chemotaxis
Cellular component: extracellular region
Genetic constraint (gnomAD): Missense variants: 0 observed, 0.14 expected, observed/expected ratio (o/e) 0, 90% interval 0 to 1.88.
Homologues: Orthologues: chimpanzee DEFB104 (100% identical), mouse Defb22 (18% identical), rat Defb22 (17% identical). Paralogues in human: DEFB104B (100% identical), DEFB116 (31% identical), DEFB108B (29% identical), DEFB115 (29% identical), DEFB129 (28% identical), DEFB108C (26% identical), DEFB118 (26% identical), DEFB121 (26% identical), DEFB127 (26% identical), DEFB123 (24% identical), DEFB135 (24% identical), DEFB119 (22% identical), and 7 more.